EGF (epidermal growth factor)
Diseases named in the same sentence as EGF in open-access papers (continued):
Sharing a sentence is not in itself a finding about the gene and the disease.
breast carcinoma (continued). "Notably, N192, N200, and N219 residues are critical for GSK3β binding; however, epidermal growth factor (EGF)-induced glycosylation at these sites antagonizes this interaction, thereby stabilizing PD-L1 in breast cancer." (PMID 41486149, 2026). "In breast cancer, it is upregulated by EGF, displacing TNS3 from actin to promote migration." (PMID 40906372, 2025). "Furthermore, YTHDC1 can bind to m6 A-modified EGF mRNA and promote EGF synthesis, thus enhancing homologous recombination repair(HR) during chemotherapy and leading to adriamycin resistance in breast cancer cells." (PMID 40483535, 2025). "Furthermore, EGF produced by TAMs in tumor tissues activates EGF receptors expressed on breast cancer cells, establishing a positive feedback loop between cancer cells and TAMs through CSF-1/EGF signaling." (PMID 40940867, 2025). "However, our on-chip indicates that KRAS activation and EGF exposure are required to promote conversion to a stem-like phenotype and induce the most robust tumor response when used to seed a mouse breast cancer model." (PMID 40487641, 2025). "Similarly, the strong interaction between PCBs and EGF underscores the significance of EGF in breast cancer pathology." (PMID 40584614, 2025). "Furthermore, METTL3 has been found to interact with the transactivation domain of EGF-induced STAT5B in the nucleus of breast cancer cells." (PMID 40507264, 2025). "This epidermal growth factor is overexpressed or amplified in approximately 20% of breast cancers." (PMID 41567886, 2025). "In addition, E2 signaling to ERK 1/2 was dependent upon the transactivation of the EGFR via the release of membrane-associated heparin-bound EGF (HB-EGF) in MDA-MB231 cells, which are ER- breast cancer cells." (PMID 40422206, 2025). "In addition, we treated MDA‐MB‐468 breast cancer cells, which over‐express the EGF receptor, with EGF and examined the expression of specific genes that are cordycepin sensitive in MCF‐7 cells." (PMID 39508147, 2025). "However, the inhibitor of carboxypeptidase from potatoes was also reported to exert cytotoxic activity by acting as an epidermal growth factor (EGF)/ transforming growth factor alpha (EGF/TGF-alpha) antagonist in the MDA-MB-453 breast cancer cell line." (PMID 38769554, 2024). "For example, breast cancers with high EGF activity have increased NRP-1." (PMID 39683699, 2024). "Moreover, epidermal growth factor (EGF) treatment made PD-L1 stabilization due to inactivation of GSK3β in breast cancer." (PMID 38638430, 2024). "Moreover, it has been documented that in basal-like breast cancer, epidermal growth factor (EGF) stabilizes PD-L1 through inactivation of GSK3β." (PMID 38660299, 2024). "Notably, in breast cancer cells, the activation of EGF inactivates GSK3β, thereby promoting the stabilization of PD-L1." (PMID 38474186, 2024). "The effect of serpin E2 breast cancer cell metastasis was induced by EGF, as evidenced by the fact that the number of lung and liver tumors in the transfection group was significantly higher than that in the negative control group after injection of MCF-7 cells overexpressing serpin E2." (PMID 38469181, 2024). "Upon EGF stimulation, RhoGDI1 phosphorylated at Ser174 binds to 14-3-3, promoting the dissociation of RhoA, Rac1 and Cdc42, which leads to their activation and results in cancer cell invasion and breast cancer metastasis." (PMID 39768163, 2024). "These experiments suggest that DOCK4 and RAC1 promote the intercalation of breast cancer cells into the brain endothelium via regulating cell elongation but not filopodial protrusions in response to endothelial-derived growth factors, such as EGF." (PMID 38762624, 2024). "Studies on integrins in breast cancer and pancreatic ductal adenocarcinoma have demonstrated that integrin signaling can increase the secretion of EGF, which may bypass the blocking effect of mAbs, such as cetuximab." (PMID 38315147, 2024).
breast carcinoma (continued). "Additionally, epidermal growth factor (EGF) stimulation has been shown to increase GFPT mRNA levels in breast cancer cells, and nicotine-induced O-GlcNAcylation and GFPT expression enhance the EMT and invasion capabilities of breast cancer cells." (PMID 39664728, 2024). "Endocytosis of GPR54 and EGFR is modulated by EGF or KP-10 stimulation in breast cancer cells." (PMID 37736108, 2023). "This study did show that the downstream results of the knockout of hMena affecting activity of EGF in the cell may be a great attribute to identify new methods for the prognosis in breast cancer patients." (PMID 38137912, 2023). "Furthermore, the addition of EGF reportedly recruited both CaM and Akt to the plasma membrane, which was suppressed by W-7 treatment, in breast cancer cell lines." (PMID 36835331, 2023). "Here we examined whether stabilin-1 can mediate clearance of EGF, an essential growth factor that promotes breast cancer progression." (PMID 36960065, 2023). "Our study demonstrates a protective role for FGF1 in MCF-7 breast cancer cells against taltobulin-induced cytotoxicity, mediated by activation of its receptors and compares its activity to EGF, another growth factor involved in breast cancer development and progression." (PMID 37509496, 2023). "We have previously shown that in breast cancer cells, epidermal growth factor and extracellular calcium activate estrogen receptor-alpha (ERα) in the absence of estradiol by increasing intracellular calcium which binds to the ligand-binding domain and activates the receptor." (PMID 38131032, 2023). "A previous study demonstrated that EGF could promote breast cancer cell survival by regulating the expression of anti-apoptotic factor Mcl1 through the MAPK-Elk1 signaling pathway." (PMID 36770773, 2023). "In summary, FGF1, EGF and their receptors are important players in breast cancer development." (PMID 37509496, 2023). "Mitogen-activated protein kinase kinase (MEK)/extracellular signal-regulated kinase 1/2 (ERK1/2) along with PI3K/AKT pathways are jointly induced by PRL and EGF through their corresponding receptors, promoting the proliferation, survival, and metastasis of breast cancer cells." (PMID 37415164, 2023). "In breast cancer, IL-17E was synergized with EGF and conferred resistance to EGFR-TKIs." (PMID 37444399, 2023). "Another study showed that LAD1 may be downstream of EGF signaling to regulate the oncogenic behaviors of mammary tumors." (PMID 36770773, 2023). "Breast cancer mice models allowed it to be demonstrated that paracrine loops established between tumoral cells and macrophages led to a synergistic EGF (Epidermal Growth Factor) and CSF1 (Colony Stimulating Factor) mediated stimulation of the invasive potential of both cell types." (PMID 36230504, 2022). "NCGC00131308 prevented the increase in active Cdc42 induced by EGF in breast carcinoma cells." (PMID 36253497, 2022). "Interestingly, EGF stimulation of breast cancer cells leads to 945 splice variances in cells with AKT1 knockdown and 442 splice variances in Inhibitor VIII-treated cells." (PMID 35892586, 2022). "For instance, WISP2 may suppress EMT in breast cancer, on the other hand WISP2 silencing promotes a stem-like cell phenotype and the loss of the IGF1 and EGF mitogenic effect in ER-α positive breast cancer cells." (PMID 35326638, 2022). "It was reported that epidermal growth factor (EGF) might play an important role in the TNT formation in rat breast cancer cells (MTLn3)." (PMID 35794526, 2022). "The activation of PTPN5 inhibits the MAPK signaling pathway induced by EGF in breast cancer cells." (PMID 35154122, 2022).
breast carcinoma (continued). "Moreover, the epidermal growth factor/Erb-B2 receptor tyrosine kinase 2 (EGF/ERBB2) signaling pathway in breast cancer cells modulated the transcription activity of ESRRA, which was associated with poor prognosis in breast and ovarian cancers." (PMID 36517562, 2022). "Other studies found that apl-1 inhibited the Wnt/β-catenin pathway through the proteasomal degradation of β-catenin and the epidermal growth factor (EGF)-dependent proliferation of breast cancer cells (MCF-7 and ZR-75-1), probably by blocking the phosphorylation of EGF receptor." (PMID 36354997, 2022). "Macrophages may also favor carcinoma cell invasion through a CSF-1/epidermal growth factor paracrine loop, as described in breast cancer." (PMID 36555673, 2022). "EGF also induces EMT through the Snail signaling pathway in breast cancer cells." (PMID 35197444, 2022). "Furthermore, they found that MSNs potentially inhibited insulin-like growth factor 1 (mediated by breast cancer) and epidermal growth factor (EGF, mediated by prostate cancer), while they induced apoptosis by increasing the activity of caspase-3, -8, and -9." (PMID 35631477, 2022). "Current studies indicate that PKCζ is important in EGF-induced breast cancer cell tropism." (PMID 36330442, 2022). "To further confirm the selectivity of LLL12B in breast cancer cells, we tested its effects on the phosphorylation of STAT3, STAT1, or ERK following the stimulation with IL-6, IFN-γ, or EGF in the T47D breast cancer cells, which express lower basal levels of P-STAT3, and in the MDA-MB-231 TNBC cells." (PMID 36009550, 2022). "Furthermore, we found that the simultaneous expression of Arf6 and GEP100 in MCF7 human epithelial-like breast cancer cells induced EGF-stimulation-dependent EMT-like changes." (PMID 36408139, 2022). "Furthermore, our results showed that HGF was a downstream effector of Cfd and more effectively enhanced the CSC properties of breast cancer PDX cells than EGF." (PMID 34439392, 2021). "Similarly, Islam and Resat used a microfluidic device to culture MDA-MB-231 breast cancer cells finding that their motility depended on the concentration and gradient of EGF." (PMID 33417986, 2021). "For example, EGF activation of AKT in breast cancer is mediated by calmodulin." (PMID 33498407, 2021). "Interestingly, FIPI (100 nM) blocked EGF-induced calcium release in both breast cancer cell lines, whereby a significant inhibition was already observed in MDA-HER2 cells after 1 min of FIPI preincubation." (PMID 33832505, 2021). "Similarly, stress and EGF induced Akt activation and promoted breast cancer progression, which developed drug resistance through AMPK-mediated Skp2 phosphorylation in this process." (PMID 34829834, 2021). "Moreover, in MCF7 and MDA-MB-231 breast cancer cell lines sE-cad shows a stronger effect than EGF, and acts additively with it." (PMID 35127732, 2021). "We seeded breast cancer cells on an extracellular matrix-coated glass-bottomed dish and in a microfluidic device with a gradient flow of epidermal growth factor (EGF), tracked individual cell movement, calculated their migration speeds, and/or followed movement direction." (PMID 34769000, 2021). "Moreover, MYH9 promoted the invasion of breast cancer cells, and the EGF-dependent phosphorylation of MYH9 resulted in increased migration." (PMID 34887392, 2021). "Moreover, it was reported that an immunoconjugate between ipilimumab and EGFR (epidermal growth factor) targeting breast cancer cells activated NK cells, and inhibited tumor cells more efficiently than each compound alone." (PMID 33810032, 2021). "PRL promotes cell motility in several breast cancer cell lines mediated through EGF." (PMID 34572912, 2021). "Additionally, epidermal growth factor (EGF) can induce EMT of breast cancer cells via the phospho-Smad2/3 Snail signaling pathway." (PMID 34422038, 2021).
breast carcinoma (continued). "In contrast, Bryant and colleagues reported that EGF-dependent E-cadherin co-internalization occurs in a breast carcinoma cell line, along with cadherin-binding proteins p120 and β-catenin; EGF stimulation resulted in Rac1-modulated micropinocytosis, rather than caveolin-mediated endocytosis." (PMID 34948155, 2021). "Additionally, Skp2 knockdown suppressed glucose uptake and glycolysis by reduced Glu1 transcription and protein expression in breast cancer cells upon EGF or HRG stimulation, repressing breast cancer development." (PMID 34068643, 2021). "Thus, we use here the allosteric inhibitor SHP099 to study the role of SHP2 on phosphoprotein dynamics at the whole proteome level following EGF stimulation of a breast cancer cell line carrying an EGFR amplification." (PMID 33755016, 2021). "However, studies show that EGF is likely to induce tumor cell invasion in breast cancer, where the overexpression of EGFR is connected with the loss of estrogen receptor and poor prognosis." (PMID 34277608, 2021). "Indeed, a markedly increased SIRT7 expression was observed when EGF signaling activity was blocked in MDA-231 breast cancer cells by erlotinib, whereas EGF stimulation accelerated SIRT7 protein turnover." (PMID 34433808, 2021). "The breast cancer cells, after 4 days stimulated by EGF+ invaded tumor farther than EGF-." (PMID 33417986, 2021). "Multiple pre-clinical investigations showed efficacy of NK-CAR cells targeting HER2 in HER2+ breast cancer, tissue-factor in TNBC, epithelial cell adhesion molecule (EpCAM) in both HER2+ and TNBC and epidermal growth factor (EGFR) in all breast cancer subtypes." (PMID 34135901, 2021). "Furthermore, EGF-stimulated induction of actin barbed ends, as well as lamellipodia extensions specifically require the p85/p110α complex in breast cancer cells." (PMID 33931587, 2021). "Overexpression of an isoform of NHS harbouring the SHD domain has been reported to inhibit the ability of MTLn3 breast cancer cells to respond to EGF by forming lamellipodia, whilst overexpression of an isoform of NHS without the SHD domain did not affect lamellipodia extension." (PMID 34584076, 2021). "ERBB2 is a member of the epidermal growth factor (EGF) receptor family of receptor tyrosine kinases, and its IgG autoantibody has been extensively assessed as a potential diagnostic biomarker for gastric cancer and breast cancer." (PMID 35140701, 2021). "In the EGFR+ HCC1937 cells, and also in basal-like EGFR+ and HER2+ HCC1954 breast cancer cells, the presence of EGF strongly enhanced both the basal and TGFβ-induced levels of subsets of these invasion genes, whereas HER2+ HCC202 cells showed similar result as MII cells." (PMID 32350443, 2020). "To determine whether LNA-mediated depletion of Rlip is also relevant in inhibition of CDE in breast cancer cells, we investigated the effect of Rlip depletion by antisense on the endocytosis of EGF-rhodamine." (PMID 32498332, 2020). "Similar results were obtained when breast cancer cells were treated with EGF, PDGF and IGF-1." (PMID 33203880, 2020). "HA has been reported as a natural ligand to CD44 receptors overexpressed in certain types of breast cancers, and ligands, such as Epidermal Growth Factor (EGF), a natural peptide ligand to Epidermal Growth Factor receptors commonly overexpressed in some tumor cells." (PMID 33353068, 2020). "Moreover, there is crosstalk between IFN-γ and epidermal growth factor in the regulation of the distribution of ExoPD-L1 and cellular PD-L1 in breast cancer cells." (PMID 33178688, 2020). "But in contrast, in breast cancer SPHK2 is required for EGF-directed cell movement." (PMID 31455837, 2020). "In this study, we utilized these in vitro transwell models in combination with bioorthogonal noncanonical amino acid tagging (BONCAT) to investigate proteomic changes in MDA-MB-231 breast cancer cells as they undergo epidermal growth factor (EGF) mediated migration and invasion." (PMID 32629869, 2020).
breast carcinoma (continued). "New research found that in most types of breast cancer patients, high levels of CCL5 in plasma promote the expression of CX3CL1 to promote breast cancer cell proliferation through epidermal growth factor signal transduction pathway, and also promote epithelial‐mesenchymal transition." (PMID 32253815, 2020). "Co-culture of ER-positive breast cancer cell lines and M2 macrophages enhanced tumor sphere formation, and in mouse models, TAM was associated with the promotion of SOX2, a CSC regulatory factor in EGF/EGFR signaling." (PMID 32726950, 2020). "Furthermore, LAD1 has been reported as a filament-binding regulator and also regulates EGF signaling-mediated breast cancer tumorigenesis." (PMID 31164716, 2020). "Taken together, these data indicated that the sustained exposure to IGFBP-1 results in increased EGFR signaling in breast cancer cells and this transition to EGF sensitivity is similar to the transition that occurs during development of tamoxifen resistance in breast cancer cells." (PMID 32435229, 2020). "Since EGFR ligands (such as EGF) and other growth factors have been shown to mediate epithelial cell repair of bronchial cells, breast cancer, and PCa cells, we hypothesized that EGF might have a role in prostate epithelial cell growth in culture as well." (PMID 33195205, 2020). "In this condition, MCF-10A might have a higher ADAM9 expression than some breast cancer cell lines as a response to additional EGF in cultural medium." (PMID 32637415, 2020). "A previous study found that the hydrophobic cytoplasmic domain of NgBR binds farnesylated Ras and further promotes the plasma membrane accumulation of Ras, which is a critical step for the activation of the epidermal growth factor (EGF)‐stimulated Ras pathway in human breast cancer cells." (PMID 32542927, 2020). "Notably, in breast cancer cell lines we found upregulation of PAPP-A expression during EGF and hypoxia-induced EMT." (PMID 32792532, 2020). "In this study, we utilized well-established transwell chamber assays, in combination with the BONCAT method and mass spectrometry to identify the nascent proteome that is synthesized when breast cancer cells undergo migration and invasion towards an EGF chemoattractant." (PMID 32629869, 2020). "Also importantly, CDE plays a crucial role in breast cancer by regulating proliferative EGF, insulin, and WNT signaling." (PMID 32498332, 2020). "IGFBP-3 inhibited the EGF-induced growth of breast cancer cells when cultured on plastic or laminin but could augment EGF-induced cell proliferation when cultured on fibronectin." (PMID 32478064, 2020). "The study, which included 311 early-stage breast cancer patients, investigated associations between preoperative serum levels of EGFR and EGFR ligands (epidermal growth factor, heparin-binding epidermal growth factor (HBEGF), amphiregulin, transforming growth factor-α and betacellulin) and survival." (PMID 33024132, 2020). "This mirrored the response of breast cancer cells migrating with iEF(+)/EGF(−)." (PMID 31428691, 2019). "The data suggests that EGF mediated induction of S100 genes could be a mechanism by which HER2-overexpressing breast cancer cells develop resistance to trastuzumab." (PMID 30736768, 2019). "Our data support the finding that EGR1 could serve as oncogene in the breast cancer and first provide the evidence that it links to EGF, ERK, EGR1, PN-1 and cell migration." (PMID 31501409, 2019). "Increasing evidence demonstrated that EGF affected the β-catenin transactivation in breast cancer." (PMID 31171012, 2019). "The induction of MAPK signaling through EGF stimulation up-regulated Mcl-1 in breast cancer cells." (PMID 31404252, 2019). "Moreover, STAT3 has been proven to mediate the EGF-stimulating growth and survival effects of human breast cancer cells in vitro and, possibly, in vivo." (PMID 31485222, 2019).